IL1B (interleukin 1 beta)
Diseases named in the same sentence as IL1B in open-access papers (continued):
Sharing a sentence is not in itself a finding about the gene and the disease.
eye infection (2 papers, 2017 to 2021). An infectious process affecting any part of the eye. "In an ocular infection model of Herpes-Simplex Virus-1, it has been shown that loss of Nlrp3 is associated with increased levels of pro-inflammatory cytokines including IL-1β and TNF-α, increased infiltration of neutrophils, and enhanced Th1 and Th17 cell responses." (PMID 34690967, 2021). "Since exacerbation of the inflammatory response is a critical event during eye infection, we tested the hypothesis that antibiotic treatments not only reduced bacterial infection but were also anti-inflammatory, by influencing IL-1β cytokine production." (PMID 28878761, 2017).
eye inflammation (2 papers, 2023). "These inflammatory mediators act synergistically with IL-1β and IL-18 to promote the recruitment of inflammatory immune cells from the bloodstream to the site of eye inflammation." (PMID 37759549, 2023).
fertility disorders (2 papers, 2009 to 2022). "Pore forming ability of GSDMD represents a drug target to block IL-1β release during inflammasome-driven sterile inflammatory diseases." (PMID 36045672, 2022). "Significantly higher levels of IL-1β, IL-6 and IL-10 were detected upon inc-stimulation of cervical cells and PBMCs from CT-positive women with fertility disorders as compared to CT-positive fertile women or controls (P < 0.05)." (PMID 19397832, 2009). "In contrast, IL-1β, IL-4, IL-5, IL-6 and IL-10 mRNA expression levels were significantly higher (P < 0.05) in cells obtained from CT-positive women with fertility disorders compared to other two groups." (PMID 19397832, 2009). "On comparing cytokine expression by cells obtained from CT-positive fertile women with those with controls and CT-positive women with fertility disorders, cells from CT-positive women with fertility disorders secreted significantly higher levels of IL-1β." (PMID 19397832, 2009).
Fibroadenoma (2 papers, 2024 to 2025). A benign tumor of the breast characterized by the presence of stromal and epithelial elements. "In patients with BC and fibroadenomas, the levels of IL-1β (p = 0.0123), IL-4 (p = 0.0001), and IL-10 (p = 0.0000) were significantly higher than the norm and statistically significantly different from the control values." (PMID 40429927, 2025). "An interesting observation was that the maximum high value of IL-1β (144.5 pg/mL) was shown in fibroadenomas and the lowest value was in HER2(+) status (122.6 pg/mL)." (PMID 39456554, 2024).
fibroids (2 papers, 2022 to 2025). "Additionally, IL-1β activates mesenchymal stem cells and the NF-κβ pathway, which are linked to the development of fibroids." (PMID 40672945, 2025). "In women of reproductive age, the highest IL-1β levels were associated with larger fibroids." (PMID 40672945, 2025). "A significant decrease in IL-1β and IL-6 was observed in the endometrium of women with fibroids, alongside a notable increase in cyclooxygenases COX1, COX2, and VEGF." (PMID 40672945, 2025).
fluorosis (2 papers, 2024). "In addition, various inflammatory indicators (TNF-α, IL-1β, NF-κB), and other fluorosis-related indicators (Mag, GSK3β) were also included to assess spinal cord injury in fluorosis rats." (PMID 39687171, 2024). "Whether inflammatory factors such as SDF-1/CXCR4, IL-6, TNF-α, NF-κB, and IL-1β play a role in the hepatic system due to fluorosis deserves further exploration." (PMID 38905184, 2024). "Therefore, the present study aimed to further investigate the role of the CXCL12/CXCR4 signaling axis and the related inflammatory factors IL-1β, TNF-α, IL-6 and NF-κB in the mechanism of fluorosis-induced liver injury at the cellular level." (PMID 38905184, 2024).
Fulminant hepatic failure (2 papers, 2011 to 2017). Hepatic failure refers to the inability of the liver to perform its normal synthetic and metabolic functions, which can result in coagulopathy and alteration in the mental status of a previously healthy individual. "In conclusion, this study illustrated the contribution of both IL-1α and Il-1β in the development and acceleration of fulminant hepatitis failure." (PMID 28953903, 2017).
gallbladder cancer (2 papers, 2020 to 2023). "After cultured with aprepitant for different time, gallbladder cancer cells generated more inflammatory cytokines including IL‐6, IL‐1β and TNF‐α." (PMID 37221457, 2023).
genital warts (2 papers, 2013 to 2024). "Notably, monitoring IL-1β transcription in genital warts infected by HPV6, the same situation could be discerned." (PMID 23935506, 2013). "This dysregulation of IL-1β expression was also found in HPV+ tissues at different stages of carcinogenesis and in persistent genital warts induced by the virus." (PMID 39258253, 2024).
giant cell tumor (2 papers, 2012 to 2016). A benign, intermediate, or malignant tumor that arises from the bone or soft tissue. "The osteoclastogenic cytokines TNF-α, IL-6 and IL-1β have been investigated in giant cell tumors (GCTs) of long bones." (PMID 22157665, 2012).
glucocorticoid resistance (2 papers, 2019 to 2023). "Irrespective of glucocorticoid resistance levels, patient levels of CRP (d = 0.23; 95% CI, −0.01 to 0.46), IFN-γ (d = 0.22; 95% CI, −0.02 to 0.47), IL-1β (d = 0.18; 95% CI, −0.24 to 0.61), and IL-2 (d = −0.12; 95% CI, −1.04 to 0.80) were all not significantly different from control." (PMID 31316402, 2019).
gram-positive bacterial infections (2 papers, 2018 to 2022). Infections caused by bacteria that retain the crystal violet stain (positive) when treated by the gram-staining method. "Upon stimulation by proinflammatory cytokines such as IL-1β and TNF-α, as an important lipit mediator, PGE2 synthesis is upregulated following Gram-negative and Gram-positive bacterial infection." (PMID 29874233, 2018).
head injury (2 papers, 2014 to 2019). Injury to the head. "The secondary injury cascades that play a role in inducing sleep following diffuse TBI likely include post-traumatic signaling that activate glia, as evidenced by increased production of pro-inflammatory cytokines, such as IL-1β, in both animal models and human head injury patients." (PMID 24416145, 2014).
hemolytic-uremic syndrome (2 papers, 2014 to 2023). Acute kidney injury associated with microangiopathic hemolytic anemia and thrombocytopenia. "Monocyte and macrophage cells are the cellular components of innate immunity that have the major role in the pathogenesis of hemolytic uremic syndrome via production of proinflammatory cytokines including soluble cytokines TNF- α and IL-1β." (PMID 25035861, 2014).
Hemophagocytosis (2 papers, 2020 to 2025). Phagocytosis by macrophages of erythrocytes, leukocytes, platelets, and their precursors in bone marrow and other tissues. "Additionally, they displayed systemic autoinflammation marked by elevated levels of IL-1β, IL-18, and IL-6, alongside cytopenia and hemophagocytosis." (PMID 41116055, 2025).
Hernia (2 papers, 2025). "In vitro, we investigated the effect of the hernia meshes on M0- and M1-like macrophages, because these types of macrophages are expected to be present early after surgery and are the main sources of IL-1β and IL-6." (PMID 40526308, 2025). "Moreover, IL-1β was increased in a murine model following hernia polypropylene mesh implantation, mirroring our findings." (PMID 40311089, 2025).
herpetic keratitis (2 papers, 2024). "Another lab reported that mice exposed to polluted air developed a severe form of herpetic keratitis with increased corneal opacity, neovascularization, and production of TNF-α, IL-1β, IFN-γ, and CCL2." (PMID 38928968, 2024). "IL-1β induces the proliferation of HSV-1 in neurons, leading to more severe herpetic keratitis in mice." (PMID 38590522, 2024).
Hip dysplasia (2 papers, 2010 to 2016). The presence of developmental dysplasia of the hip. "As expected, low TNF-α, IL-1β and IL-6 expression levels were obtained in normal hip dysplasia tissues and in tissues after mechanical loosening." (PMID 26004143, 2016). "We conclude that intracapsular pressure is elevated in hip dysplasia, that it varies with the position of the hip, and that there is a correlation between an increase in IL-1β cytokine and both an increase in the volume of joint fluid and a change in intracapsular pressure." (PMID 20367415, 2010).
HIV-associated dementia (2 papers, 2020 to 2022). "In a tri-culture model of all three cell types, HIV infection of microglia led to increased production of proinflammatory cytokines (e.g., IL-1β, IL-1α, TNF-α), similar to what has been observed in postmortem tissue from HIV encephalitis cases that showed elevated IL-1β in infected microglia." (PMID 36325520, 2022).
homocystinuria (2 papers, 2021 to 2022). An autosomal recessive inherited metabolic disorder caused by mutations in the CBS, MTHFR, MTR, and MTRR genes. "CBS deficiency specifically causes a condition known as homocystinuria, which is characterized by elevation of proinflammatories such as IL-1b, IL-6, IL-8, and TNF-α." (PMID 35116090, 2022). "Proinflammatory cytokines other than IL-6, namely IL-1α, IL-1β and TNF-α, are increased in a mouse model of homocystinuria and a range proinflammatory cytokines and chemokines [IL-1α, IL-6, TNF-α, IL-17, IL-12 (p70), MIP-1α and MIP-1β] are also elevated in homocystinuria patients." (PMID 34251022, 2021).
hookworm infection (2 papers, 2011 to 2019). "In this analysis, we also found that hookworm infection among pregnant women was associated with elevated Th1 (IL-1β and IFN-γ) cytokines, as well as IL-5 and CXCL8 in blood collected from the maternal-fetal interface." (PMID 31188820, 2019). "In unstimulated PBMC cultures from negative, nonendemic individuals lower concentrations of inflammatory IL-1β, IL-6, and TNF-α were detected when compared with participants with hookworm infection." (PMID 21772981, 2011).
Hyper IgD syndrome (2 papers, 2022 to 2025). "In the Hyper IgD syndrome (HIDS), the affecting gene encoding MVK is responsible for increased mevalonic acid, IgD, and IL-1β in the serum." (PMID 35464438, 2022).
Hyperoxaluria (2 papers, 2021 to 2024). Increased excretion of oxalates in the urine. "Hyperoxaluria-induced renal NLRP3 upregulation and increased caspase-1 activity and renal content of IL-1β in HP kidneys were reduced by TRPV1 inhibition." (PMID 34201387, 2021). "Because there were parallel changes in TRPV1, ALOX12, and NLRP3 expression as well as caspase-1 activation and IL-1β formation in HP kidneys, we examined whether inhibition of TRPV1 would ameliorate hyperoxaluria-induced renal inflammation and tubular injury." (PMID 34201387, 2021).
hyperreactivity (2 papers, 2016 to 2025). "Next, to investigate the role of c-Kit signaling on IL-1β/IL-23–driven ILC3 activation and lung pathogenesis, we compared IL-1β/IL-23–induced neutrophilic inflammation, airway hyperreactivity (AHR), and ILC3 responses between c-Kit deficient (KitW-sh) mice and their WT counterparts." (PMID 40674143, 2025). "Moreover, IL-1β, IL-6 and IL-23 are known to induce IL-17A production in Th17 cells and are thereby linked to airway hyperreactivity related to obesity." (PMID 27087690, 2016).
Hypokalemia (2 papers, 2024 to 2025). An abnormally decreased potassium concentration in the blood. "Additionally, prolonged hypokalemia affects the proliferation and differentiation of T cells and monocyte-macrophages, as well as the expression of pro-inflammatory cytokines such as IL-1β, IL-6, and TNF-α." (PMID 40783707, 2025).
hypoparathyroidism (2 papers, 2020 to 2022). Hypoparathyroidism is an endocrine disorder in which the parathyroid glands in the neck do not produce enough parathyroid hormone (PTH). "Cytokines, notably interleukin (IL)-1β and IL-6, lead to an upregulation of calcium-sensing receptor (CaSR) on parathyroid glands, increasing the sensitivity of the parathyroid cells to circulating calcium, resulting in a state of acquired relative hypoparathyroidism." (PMID 33490095, 2020).
idiopathic dilated cardiomyopathy (2 papers, 2016 to 2022). Decreased function of the heart associated with cardiac enlargement and congestive heart failure, of unknown cause. "This is in line with an investigation that studied patients with idiopathic dilated cardiomyopathy, which also reported IL-1β to be the final predictor of death." (PMID 36014020, 2022).
IgG4-related disease (2 papers, 2018 to 2024). "It was found that in IgG4-related disease, M2 macrophages promote the production of several fibrogenic cytokines (IL-33, IL-1β, and TGF-β) via NF-κB signaling, leading to severe fibrosis in the affected organs." (PMID 39328595, 2024). "Currently, fibrosis of IgG4-related disease is thought to be induced by profibrotic cytokines such as transforming growth factor beta 1 (TGFB1), interleukin 1 beta (IL1B) and interferon gamma (IFNG), which are secreted by regulatory T cells (Tregs) and CD4-positive cytotoxic T cells." (PMID 29439708, 2018). "Our results suggested the profibrotic cytokines TGFB1, IL1B and IFNG induce fibrosis and that Tregs might produce some of these cytokines in IgG4-related thymitis as well as in the other affected lesions of IgG4-related disease." (PMID 29439708, 2018).
imbalance (2 papers, 2017 to 2023). "Among the PwP, changes in plasma EV-derived IL-1β, TNF-α and IL-6 levels were significantly associated with changes in the severity of postural instability and gait disturbance (PIGD) and cognition." (PMID 36897204, 2023). "APS can efficiently inhibit Cd-induced immune imbalance in chicken PBLs through the regulation of MDA5/NF-κB signaling, and it can decrease Cd-induced expression of cytokines (IL-1β, IL-6, and TNF-α)." (PMID 28946702, 2017).
infectious colitis (2 papers, 2017 to 2024). A viral or bacterial infectious process affecting the large intestine. "In an in vivo infectious colitis model, administration of selected C1 coumarin derivatives reduced pathogen loads, the number of inflammatory immune cells (Th1 cells and Th17 cells), and inflammatory cytokine levels (IL-6 and IL-1b) in the intestinal tissue after pathogen infection." (PMID 39081865, 2024).
intestinal cancer (2 papers, 2022 to 2023). "This was also associated with reducing IL-1β, Cox-2, and IL-17RC expression suggesting proinflammatory and protumorgenic roles of IL-17F in intestinal cancer." (PMID 35012470, 2022).
Intraventricular hemorrhage (2 papers, 2017 to 2026). Bleeding into the ventricles of the brain. "It is important to emphasize that the primary objective of this study was not to dissect IL1B signaling per se, but rather to establish a robust human SVZ‐on‐a‐chip model to investigate mechanisms of neonatal intraventricular hemorrhage." (PMID 41133939, 2026).
iron disorders (2 papers, 2022 to 2025). "No detectable levels of IL-1β and IL-6, the main cytokines involved in iron disorders, were recorded both in basal and Spike/bLf-stimulated conditions (data not shown)." (PMID 36297546, 2022).
Kaposi's sarcoma (2 papers, 2013 to 2024). A malignant neoplasm characterized by a vascular proliferation which usually contains blunt endothelial cells. "The herpes virus KSHV is linked to Kaposi’s sarcoma, characterized as an angioplastic tumor formation that necessitates a consistent IL-1β environment." (PMID 38590522, 2024).
Left ventricular dilatation (2 papers, 2024 to 2025). Enlargement of the chamber of the left heart ventricle. "Pro-inflammatory cytokines, such as TNF-α and IL-1β, cause cardiac myocyte hypertrophy, contractile dysfunction, and left ventricular dilatation and modulate the interstitial matrix of the heart." (PMID 38813367, 2024). "During the subacute phase of AMI, IL-1β is known to exert deleterious effects on left ventricular dilatation and contractility, related to a reduction in β-adrenergic receptor responsiveness." (PMID 40428204, 2025).
left ventricular hypertrophy (2 papers, 2024 to 2025). Enlargement of the LEFT VENTRICLE of the heart. "Elevated levels of TNF-α and IL-1β have also been associated with reduced survival in chronic HD patients, and TNF-α has been associated with left ventricular hypertrophy in these patients." (PMID 40004669, 2025).
lichen sclerosus (2 papers, 2019 to 2022). "Serpin A1 expression is enhanced by the cytokines EGF, TNF-α, INF-γ, and IL-1β in cutaneous SCC cells and the latter three are also upregulated in lichen sclerosus." (PMID 30607583, 2019). "However, there is almost no data reflecting the expression of cytokines genes in the LS tissue what prompted us to determine the mRNA levels of IL-1A, IL-6, IL-1B, IL-1RN, TGF-β1 and INF-γ genes in a large sample of penile lichen sclerosus tissue as compared to control penile tissues." (PMID 35103930, 2022).
Lipedema (2 papers, 2020 to 2022). Disorder of adipose tissue characterized by symmetric and bilateral enlargement of the lower extremities due to abnormal deposition of subcutaneous fat often in obese women. "Importantly, the expression of IL1b, the IL1R1 and other IL1b related genes were downregulated in the RNA sequencing in our lipedema samples." (PMID 36605202, 2022).
malignant mesothelioma (2 papers, 2016 to 2021). A malignant neoplasm of the pleura or peritoneum, arising from mesothelial cells. "Other cytokines that were shown to be significantly affected in both pleural fibrosis and malignant mesotheliomas include IL-6, IL-1b, and IL-8, possibly through inflammasome activation." (PMID 26080392, 2016). "IL-1β, a member of the NOD-like receptor signaling pathway, is known to contribute to malignant transformation of malignant mesothelioma, suggesting that it may be involved in the formation of the fibroblast-like morphology of HOMC-A4." (PMID 34663305, 2021).
morbid obesity (2 papers, 2022). An excess of body weight, normally defined as an individual with a body mass index greater than 35 or a body weight greater than one hundred percent of ideal body weight. "Interestingly, plasma caspase-1 concentrations normalized in both groups, whereas plasma IL-1β levels normalized only in patients with morbid obesity and normal glucose tolerance suggesting the persistence of a systemic inflammatory condition in people with T2D." (PMID 36012889, 2022).
muscle degeneration (2 papers, 2014 to 2025). "In particular, inflammation, which involves cytokines such as Interleukin-1β (IL-1β), is recognized as a contributing factor to age-related cognitive impairments and muscle degeneration." (PMID 40469587, 2025).
myonecrosis (2 papers, 2019 to 2025). "NLRP3-mediated necrosis or induction of IL-1β appears to be involved in the myonecrosis induced by PFO." (PMID 31708887, 2019). "On the other hand, it remains to be elucidated whether IL-1β induced by inflammasome activation is responsible for the PFO-mediated myonecrosis." (PMID 31708887, 2019). "Meanwhile, α-toxin triggers myonecrosis by essentially different mechanisms, in the absence of obvious inflammation, such as inflammasome activation or IL-1β induction." (PMID 31708887, 2019).
nematode infection (2 papers, 2018 to 2019). "Finally, we determined whether the inflammatory responsiveness of Nlrp3 and Il1b is influenced in vivo by nematode infection triggered alternative macrophage activation." (PMID 29343442, 2018).
nephrocalcinosis (2 papers, 2020 to 2021). Nephrocalcinosis is a disorder that occurs when too much calcium is deposited in the kidneys. "Moreover, immunohistochemistry analysis revealed high expression levels of NLRP3, caspase-1, and IL-1β in nephrocalcinosis samples." (PMID 34512861, 2021).